HLA-DRA (major histocompatibility complex, class II, DR alpha)
Diseases named in the same sentence as HLA-DRA in open-access papers (continued):
Sharing a sentence is not in itself a finding about the gene and the disease.
sarcopenia (1 paper, 2024). Progressive decline in muscle mass due to aging which results in decreased functional capacity of muscles. "Our research indicated MAP 3K3, MFGE8, COL15A1, HP, and HLA‐DRA may serve as promising targets for sarcopenia, while the effectiveness of zinc supplementation and collagenase clostridium histolyticum for sarcopenia requires further validation." (PMID 38644354, 2024). "The transcription level of HLA‐DRA in skeletal muscle tissue (per 1 SD increase) was associated with lower ALM (beta: −0.09, 95% CI: −0.11 to −0.08, P = 5.4*10−36) and lower grip strength (OR: 1.13, 95% CI: 1.07–1.20, P = 1.8*10−5), indicating the increased risk of sarcopenia." (PMID 38644354, 2024). "The results revealed that six potential druggable genes (HP, HLA‐DRA, MAP 3K3, MFGE8, COL15A1, and AURKA) passed the colocalization analysis and were present in more than one QTL datasets or sarcopenia‐related traits." (PMID 38644354, 2024). "Based on these integrated datasets, our study provides potential evidence for the genetic colocalization of six drug target genes (HP, HLA‐DRA, MAP 3K3, MFGE8, COL15A1, and AURKA) with sarcopenia." (PMID 38644354, 2024). "Interestingly, the impact direction of increased HP and down‐regulated HLA‐DRA is the same as that on sarcopenia, implying that drug targets on HP and HLA‐DRA for sarcopenia may also be beneficial for these diseases, including sarcopenia and dyslipidaemia diseases." (PMID 38644354, 2024). "Among them, HP, HLA‐DRA, and MAP 3K3 were related to at least two sarcopenia‐related traits." (PMID 38644354, 2024).
substance abusers (1 paper, 2016). "Among substance abusers, a slight strengthening of the signal for the variants near the HLA-DRA gene on 6p21.32 was observed, but the signal was diluted for the variants on 6p21.2 (data not shown)." (PMID 27598967, 2016).
thymoma (1 paper, 2022). A neoplasm arising from the epithelial cells of the thymus. "The positive correlation between the CD74 and HLA-DRA expression in our study was also found in another report on invasive thymomas." (PMID 35208514, 2022).
toxoplasmosis (1 paper, 2020). A parasitic disease contracted by the ingestion or fetal transmission of toxoplasma gondii. "Moreover, based on the 51 common supertargets of the cohort and personalized approach the down-regulated genes HLA-DRA and HLA-DRB1 were found to be prominently involved in all seven highlighted pathways, while the up-regulated gene LAMB3 played an additional role in toxoplasmosis." (PMID 33273683, 2020).
ZIKV infection (1 paper, 2022). "ZIKV-infected macrophages were further analyzed, which showed that the transcription of HLA-DRA, but not CD163, was upregulated indicating that ZIKV infection polarized THP-1-differentiated macrophages (M0) to proinflammatory M1 phenotype macrophages." (PMID 35446851, 2022).
tumor (143 papers, 2008 to 2026). "RNA sequencing results revealed significant differences in gene expression, with key genes (upregulated CXCR4, OPCML, and S100A2, and downregulated ATP1A3, CHL1, HLA-DRA, and IL-1β) associated with tumor invasiveness." (PMID 41374320, 2025). "While the tumor-associated macrophage (TAM) markers, as well as CD68 and HLA-DRA as both M1/M2 and tumor-associated macrophage (TAM) markers were highly expressed in each macrophage subtype, indicating they were all TAMs." (PMID 35361264, 2022). "A causative relationship has been found between MHC-II and/or HLA-DRA and increased tumour-infiltrating lymphocytes, associated with more favourable outcomes in cancer patients." (PMID 35208514, 2022). "By performing a differential analysis between the two tumor cell compartments, we found that numerous genes associated with antigen presentation (e.g., HLA-DRA, CD74) were intensively upregulated in APHC, while a variety of metabolic enzymes (e.g., CYP3A5, ALDOB) were highly expressed in ANHC." (PMID 37336873, 2023). "An upregulation of HLA-DRA expression is associated with antitumour immune response, whereby it functions in presenting tumour-associated antigens (TAA) on cancer cells that trigger CD4+ Th1 cells and NK cells, with the production of IFN-γ, an antitumour cytokine." (PMID 35208514, 2022). "In addition, HLA-DRA was associated with an inflamed tumor microenvironment (TME) and could predict the response to ICB in NSCLC." (PMID 35794593, 2022). "To validate the dual epithelial-immune feature of MHC-II+ cancer cells, we performed multiple immunofluorescence staining in UC tissues and confirmed the coexpression of epithelial markers (pan-CK) and HLA-DRA in single cancer cells from MI tumours." (PMID 41281745, 2025). "Compared to other EC subtypes,EC4 exhibited elevated expression levels of multiple genes implicated in antigen presentation (HLADRB1,HLA-DRB5,and HLA-DRA),immune cell recruitment (SELP,LIFR, and ACKR1),and anti-tumor inflammation (CCL14,IFITM1)." (PMID 41394809, 2025). "Spatial transcriptomics indicated that regions enriched for PSCA+ tumor cells also showed enrichment of the C11_HLA-DRA cluster, consistent with a potential local communication hub." (PMID 41514658, 2025). "This study expands our understanding of the regulation of ts-MHC-II expression and provides evidence that cuproptosis and HLA-DRA promote the body’s anti-tumor immune response." (PMID 38931345, 2024). "Cuproptosis has the potential to reverse the suppressive tumor immune microenvironment of ccRCC by stimulating HLA-DRA expression and modulating immune cells and related immune responses." (PMID 38931345, 2024). "1D09C3 (DB05121) targeting HLA-DRA is investigated for killing tumor cells by inducing programmed cell death." (PMID 38166628, 2024). "HLA-DR, of which HLA-DRA is a subunit, is known to be involved in inhibiting tumor growth and plays a crucial role in human cancer." (PMID 39346909, 2024). "Genes such as COL1A1, COL1A2, and COL3A1, which are implicated in the tumor microenvironment, and immune-related genes, such as THY1, IRF5, and HLA-DRA, exhibited significant expression level changes." (PMID 38672562, 2024). "When ctDNA detection was combined with the level of tumour mutational burden (TMB) and a tumour-derived interferon signature (including HLA-DRA, CXCL9/10/11, GZMA, PRF1, CCR5, IFNG, IDO1 and STAT1), the predictive value of the combined score was enhanced." (PMID 38201222, 2023). "Tumor-associated macrophages (TAMs) were identified by CD68, CD14, CD163 and HLA-DRA and cancer-associated fibroblasts (CAFs) were characterized by COL1A1, COL3A1, MMP2, and SPARC." (PMID 37007745, 2023). "We correlated the expression of HLA-DRA and immune correlation in the LGG dataset of The Cancer Genome Atlas (TCGA) to ascertain the significance of HLA-DRA expression within the tumor samples." (PMID 35585639, 2022).
tumor (continued). "Differential analysis showed that proliferation and antigen presentation genes, such as STMN1 and HLA‐DRA, were slightly up‐regulated in tumour cells, whereas differentiation molecules, such as KRT13, HOPX and CD24, were highly expressed in normal cells." (PMID 35608199, 2022). "We found that myeloid cells from two clusters (aMΦ, bMΦ), characterized by the expression of tumor-associated macrophage genes (CD163, CCL4, APOE, and HLA-DRA) were strongly connected to the CD8+ exhausted and CD4+ Th1 T cell clusters." (PMID 35177622, 2022). "Taken together, the data suggested that HLA-DRA is a pan-cancer classifier for immuno-hot tumors except for a few tumor types." (PMID 35794593, 2022). "These immuno-scores, including TMB (tumor mutational burden), PD-L1, CTLA4, or immune-related genes (HLA-B, HLA-A, HLA-DRA), expand knowledge in tumor immune status and provide a potent prediction tool for the future." (PMID 36451642, 2022). "The results showed that the expression of HLA-DRA protein was significantly downregulated in tumor tissues." (PMID 35794593, 2022). "Among the identified DE genes in NSCLC PBL T cells and tumor T cell clusters, HLA-DRA, HLA-DRB1, OAS1, and CD74 had concordant prognostic indications at the mRNA and protein expression levels in bulk NSCLC tumors with resectable disease." (PMID 35804895, 2022). "The expression levels of FCGR2B, IL10RA, and HLA-DRA in tumor samples (n=177) were significantly higher (q value < 0.001; log2FoldChange > 1) than in normal pancreatic tissue (n=171; from GTEx database)." (PMID 33845841, 2021). "HLA-DR is expressed from other immune cells (such as antigen presenting cells), suggesting the decreased expression of the total tumor is due to the downregulation of HLA-DRA in other cells." (PMID 33796222, 2021). "According to HLA-DRA's alteration and considering it belongs to HLA family, the expression of the HLA can affect T-cell recognition of tumor antigen and influence the local immune status." (PMID 33585439, 2020). "We identified an increased expression of genes that were previously found in the astrocytes from tumor specimens, (HLA-DRA, CHI3L1 SERPINA1, CCL18, CD37, and CD274)." (PMID 31186414, 2019). "In the reactive astrocytes from the tumor we identified an increased expression of immune associated genes such as CHI3L1, HLA-DRA, CD274, HLA-DRB3, CD37, as well as genes that contributed to proliferation (MKI67, ANXA2) and complement components (C1S, C1R)." (PMID 31186414, 2019). "In early-stage MF, we observed gene expression differences in cells of both the stroma and the immune system, with keratinocytes exhibiting increased interferon response and proliferation (STAT1, ICAM1, HLA-DRA, GJB2), while fibroblasts displayed tumour-associated programs (CXCL2, TNFAIP6, CEBPD)." (PMID 41888970, 2026). "Subsequent labeling of DEGs in the signaling pathways confirmed that cuproptosis may alter the anti-tumor orientation of the TME in an HLA-DRA-dependent manner through activating T-cell receptor signaling pathways and NK cell activity." (PMID 38931345, 2024). "HLA-DRA was an HLA class II alpha chain paralogue, an adaptive immunity gene involved in antibody-mediated immune response and macrophage activation, ultimately affecting tumor cell growth." (PMID 38877387, 2024). "Therefore, we aimed to investigate novel approaches for enhancing HLA-DRA expression on the surface of tumor cells." (PMID 38931345, 2024). "Neutrophils of cluster 3 (Neu_C3_VEGFA, CD74+/HLA‐DRA+) displayed a mixed phenotype with angiogenesis, lipid metabolism‐related, and antigen‐presentation characteristics and they enriched in both the leading‐edge and tumor‐core region." (PMID 39716897, 2024). "Consequently, a detailed analysis of HLA-DRA was conducted to explore its potential contribution to ccRCC anti-tumor immunity and immunotherapy." (PMID 38931345, 2024). "This study also found that HLA-DRA was expressed in tumor and immune cells." (PMID 37511958, 2023).
tumor (continued). "Importantly correlation analyses showed significant co-expression between CMKLR1 and genes specific of tumor associated macrophages (TAM) such as CD14, CD163, MRC1 and HLA-DRA in BC and MPM." (PMID 37539056, 2023). "Our imaging suggested similar interactions may be occurring in human non-tumor-associated dura as we observed co-localization of CD4+ T cells and HLA-DRA+ cells in addition to CD8+ T cells and CD163+ macrophages near CD31+ stained vasculature." (PMID 35534852, 2022). "Moreover, HLA-DRA was negatively correlated with tumor purity but positively correlated with TIIC levels in most cancer types." (PMID 35794593, 2022). "Strikingly, for genes in cluster ii), which are specifically up-regulated in AAS, high expression of 7 of the top 10 genes (C3, CD74, HLA-DRA, STRA6, IGFBP4, PIGR, and TNIP1) was strongly associated with better cumulative survival than tumours with low expression of these genes." (PMID 32218455, 2020). "We elected to use a 90% cutoff to distinguish cases with reduced HLA-DRA expression on the basis that this was the most predictive of outcome and would identify patients where tumor cells might be capable of escaping immune surveillance." (PMID 26500140, 2016). "Furthermore, a number of interferon (IFN) response genes (BST2, CD74, HLA-DMA, HLA-DPB1, HLA-DQB1, HLA-DRA, HLA-DRB1, and IRF8) were upregulated in C10 compared to the other clusters, whereas genes associated with tumor suppression and apoptosis (TFF1 and TFF2) were downregulated." (PMID 37370788, 2023). "Interestingly, HLA-DRA was negatively correlated with tumor purity." (PMID 35794593, 2022). "We obtained results on the correlation between TPPP3 expression and marker genes of tumor infiltration-associated immune cells, including CD8+T cells (CD8A and CD8B), B cell (CD19 and CD79a), and Myeloid dendritic cell (HLA-DPB1, HLA-DQB1, HLA-DRA, HLA-DPA1, CD1C, NRP1, and ITGAX)." (PMID 33083464, 2020). "To determine the TME of the HLA-DRA high- and low-expression groups, we calculated the ESTIMATE scores and estimated the purity of stromal, immune, and tumor cells." (PMID 38931345, 2024). "The top 100 genes found to be co-expressed with CD74 were examined using GEPIA2.0, finding that the top five genes (HLA-DMA, HLA-DPA1, HLA-DPB1, HLA-DRA, and HLA-DRB1) were highly correlated with CD74 in most tumor types." (PMID 38582956, 2024). "The results showed a significant correlation between CHST11 and certain tumor immunostimulators (CD28, IL2RA, and TNFSF13B), tumor immunoinhibitors (CD96 and LGALS9), and MHC proteins (HLA-DRA and HLA-DMB)." (PMID 38565604, 2024). "Antigen-presenting CAF were found in various metastatic tumor foci, which exhibited high expression of HLA-DRA, HLA-DRB, and other MHC genes, potentially contributing to anti-tumor immunity." (PMID 38278958, 2024). "TIMELESS expression was significantly negatively correlated with neutrophil biomarkers (CEACAM8) and dendritic cell biomarkers (HLA-DPB1, HLA-DQB1, HLA-DRA, HLA-DPA1, CD1C) in TCGA LUAD tumor tissues." (PMID 38261568, 2024). "Through transcriptional trajectory analysis, we discovered a specific cluster of tumour cells in LSCC with COPD that exhibited high expression levels of MHC II‐related genes, including CD74, HLA‐DRA and HLA‐DMA." (PMID 39113235, 2024). "The highest levels of expression in tumor tissue were observed for CD74 (Mean ± SEM = 10.94 ± 0.08), IFI27 (Mean ± SEM = 9.63 ± 0.12), and HLA-DRA (9.3 ± 0.1)." (PMID 39457004, 2024). "Cluster Fib_5 prominently expressed MHC-II genes (HLA-DQA1, HLA-DQA2, HLA-DQB1, HLA-DRB5, HLA-DRB1, HLA-DRA, HLA-DPA1, and HLA-DPB1), indicating their role as antigen-presenting cells with tumor-suppressing effects." (PMID 37533434, 2023). "As a result, we found that CD163, CD74, S100A4, S100A12, HLA-DRA, and HLA-DRB1, which are usually highly expressed in myeloid cell, were also highly expressed in tumor cells of cluster 6; thus, we termed this cluster myeloid-like tumor cells." (PMID 37138326, 2023).
tumor (continued). "Multiple genes (HLA-DRA, HLA-DRB1, OAS1, and CD74) differentially expressed in NSCLC B cells, peripheral blood lymphocytes, and tumor T cells had concordant prognostic indications at the mRNA and protein expression levels." (PMID 35804895, 2022). "In the TCGA dataset, the expression levels of CD2, HAVCR2, HLA-C, HLA-DRA, HLA-E, KLRK1, and TYROBP were all significantly downregulated in tumor tissues compared with para-tumor tissues." (PMID 35794593, 2022). "As the disease progresses to HGCIN and SCC, increased synthesis of HLA-DRA protein recruits immune support via CD4+ T cells, leading to more favourable CD8+ T-cells responses and thus preventing tumour invasion." (PMID 35208514, 2022). "Among these candidates, we found that human leukocyte antigen-DR alpha (HLA-DRA) was downregulated in NSCLC tissues and both tumor and immune cells expressed HLA-DRA." (PMID 35794593, 2022). "Considering the immune activation in FAC2 bulk samples, we checked the expression of MHC-I (HLA-A and HLA-B) and MHC-II (HLA-DRA) molecules, and found their upregulation in FAC2-like tumor cells." (PMID 35342352, 2022). "The differential analysis also confirmed the high expression of CD74, HLA-DRA, C7, CCL12, and CCR3 in CAFs from P-LN but lower expression of VIM, APOD, MMP11, TAGLN, and CDKN2A compared with that in the primary tumor." (PMID 36569924, 2022). "The refined six gene tumor immune signature (IDO1, CXCL10, CXCL9, HLA-DRA, STAT1, IFNG) was carried on a sample of cases representative of the Sema4D HIS subtypes using basic nSolver analysis." (PMID 33776991, 2021). "Multiplex immunofluorescence staining was performed to quantify CD163, HLA-DRA and CD14 expression in the tumour area annotated by AMACR staining." (PMID 32908142, 2020). "Observation of CD3+CD8+ T lymphocyte and HLA‐DRA+CD163+ macrophage infiltration in these tumors, and demonstration of GBP1 expression in tumor cells also attested to the activation of this pathway." (PMID 31025552, 2019). "The transcriptional level of HLA-DRA was markedly reduced, consistent with decreased cell surface MHC class II expression in tumour sera-cultured DCs." (PMID 28350008, 2017). "Tumor stromal pathways are also in evidence with the common genes including; TLR4, TLR7, HLA-DRA, HLA-DQA1, CXCR4, FOS and TGFB2 (immune surveillance and chemokine pathways) and NF2, ITGA7, PGF, ITGA4, PDGFD and PARVA (focal adhesion)." (PMID 23226201, 2012). "In addition, enhanced expression of proteins related to antigen processing and immune activation, including HLA-DRA, ITGAM, and C1QC, reflected a strong inflammatory phenotype within the tumor tissue." (PMID 41480141, 2025). "HLA-DRA also showed a surprising positive correlation with CCL4, CCL5, CXCL9, and CXCL10, indicating its beneficial role in the human immune response through inducing immune cell infiltration and improving tumor clearance in the body." (PMID 38931345, 2024). "TIMELESS expression in LUAD tumor tissues was significantly negatively correlated with neutrophil biomarkers, dendritic cell biomarkers (HLA-DPB1, HLA-DQB1, HLA-DRA, HLA-DPA1, CD1C) and an immunophenoscore that predicted outcomes associated with the use of immune checkpoint inhibitors." (PMID 38261568, 2024). "However, the expression of genes participating in AP (e.g., HLA‐DRA/DMB and CD74) and anti‐tumour immunity (e.g., GBP1, IFNG and TNFRSF9) were significantly higher in the TS, while genes involved in angiogenesis (e.g., VEGFA) was significantly higher in TN." (PMID 37491740, 2023). "The increased transcripts for EGR1, interferon-induced proteins (IFI6, IFIT1, IFIT3, IFIT5), and MHC class II (HLA-DRA) indicated strong stimulation of IFN signaling, which could result in activation of macrophages in the tumor microenvironment." (PMID 37834191, 2023).